LTF (lactotransferrin)
Diseases named in the same sentence as LTF in open-access papers (continued):
Sharing a sentence is not in itself a finding about the gene and the disease.
glioma (7 papers, 2021 to 2025). A benign or malignant brain and spinal cord tumor that arises from glial cells (astrocytes, oligodendrocytes, ependymal cells). "Public datasets also indicate that LTF expression is associated with glioma grade and molecular subtypes." (PMID 40960773, 2025). "We further analyzed the distribution of LTF expression in different molecular subtypes of glioma using TCGA, CGGA, and Rembrandt datasets." (PMID 40960773, 2025). "In the present study, however, LTF was overexpressed in glioma samples and was indispensable for the malignant phenotypes in the in silico and in vitro experiments." (PMID 37545464, 2024). "Based on GSE4290 and GSE12657 datasets which also contained astrocytoma and oligodendroglioma samples, we next explored the LTF expression in these two low-degree gliomas." (PMID 38763993, 2024). "Taken together, the LTF expression level is significantly increased in GBM this highest WHO grade glioma." (PMID 38763993, 2024). "Compared with WHO IV grade glioma (GBM), LTF was significantly downregulated in lower grade gliomas (WHO II and WHO III)." (PMID 38763993, 2024). "Our results highlighted the role of PTX3 and TIMP1 which were previously considered in glioma tumorigenesis as well as LTF as a new potential biomarker." (PMID 36153549, 2022). "In our study, we also observed an increase in the expression level of LTF in patients with stage G3/G4 glioma compared to G2." (PMID 35454784, 2022). "In addition, we found that LTF expression levels were significantly increased in high grade glioma samples compared to low grade samples using TCGA, CGGA, and Rembrandt datasets." (PMID 40960773, 2025). "Based on our results above, compared with WHO II-III grade glioma, LTF was significantly upregulated in higher grade gliomas (WHO IV), we hypothesized that the LTF expression level would correlate with the prognosis of glioma patients and GBM patients." (PMID 38763993, 2024). "After treatment with different doses of DFO and erastin, the transcriptional activities of HMOX1, LTF, and STEAP3 were reduced in both U87 and U251 glioma cells, indicating that these genes played a role in iron metabolism regulation." (PMID 37545464, 2024). "Single‐cell analysis of data from purified malignant glioma cells showed that HMOX1, LTF, and STEAP3 were predominantly expressed in mesenchymal‐like cell clusters facilitating intratumoral mesenchymal shift over time." (PMID 37545464, 2024). "HMOX1, LTF, and STEAP3 knockdown in glioma cells significantly reduced cell proliferation, colony formation, migration, and malignant invasion." (PMID 37545464, 2024). "The data indicated that HMOX1, LTF, and STEAP3 had relatively higher expressions in glioma cells compared to most other cancer cell lines." (PMID 37545464, 2024). "The top 20 network analysis indicated that PTX3, TIMP1, CHI3L1, LTF and IGFBP3 comprise a crucial role in gliomas progression." (PMID 36153549, 2022). "High DEGs in grade II gliomas included NNMT, MFAP5, APCDD1L-AS1, C7orf57, HP, SERPINA5, and LTF and some highly downregulated DEGs included ABCA4, PDE6A, GRP, RD3, and TMEM72." (PMID 33948562, 2021). "Finally, the top three genes (STEAP3, LTF, and HMOX1) with the greatest importance were chosen as key prognostic IMRGs for gliomas." (PMID 37545464, 2024). "HMOX1, LTF, and STEAP3 were identified as the most essential IMRGs in gliomas." (PMID 37545464, 2024). "These in vitro findings demonstrated that HMOX1, LTF, and STEAP3 could facilitate the malignant progression of glioma cells." (PMID 37545464, 2024).
ovarian carcinoma (7 papers, 2020 to 2025). A malignant neoplasm originating from the surface ovarian epithelium. "Lactotransferrin (LTF) variant rs112647 was found to have a significant role in the physiology of ovarian cancer in Chinese Han patients." (PMID 40142220, 2025). "The expression of CYBRD1, LRP2, TFRC, SLC22A17, HEPH, SLC39A14, and PCBP2 involved in iron import was associated with poor OS of ovarian cancer, whereas the expression of LCN2, CP, SLC46A1, STEAP3, and LTF in this process was associated with improved OS in ovarian cancer." (PMID 38186569, 2023). "In context of cancers, omentin has been shown to have differential effects; in ovarian cancer, it prevents progression and metastatic dissemination via interaction with lactotransferrin (LTF)." (PMID 33450975, 2021). "Conversely, 8 genes showed increased expression in ovarian cancer tissues, including LCN2, CP, TFR2, LRP2, MELTF, LTF, SLC11A2, and STEAP3." (PMID 38186569, 2023). "Further studies demonstrate that ITLN1 suppresses lactotransferrin’s effect on ovarian cancer cell invasion potential and proliferation by decreasing MMP1 expression and inducing a metabolic shift in metastatic ovarian cancer cells." (PMID 32669559, 2020).
periodontitis (7 papers, 2022 to 2025). An acute or chronic inflammatory process that affects the tissues that surround and support the teeth. "In fact, these findings are contradicted by a recent study aiming to verify a link between DEFB1 and LTF polymorphisms and periodontitis." (PMID 37372382, 2023). "In contrast, lower levels of Lactotransferrin, Prolactin-inducible proteins, Salivary acid proline-rich phosphoprotein 1/2, and Cystatin (mainly S, SA, and SN) were shown to be associated with periodontitis." (PMID 36355174, 2022). "Some functional genetic variants of LTF have been associated with an increased susceptibility to periodontal disease, with a lower frequency of AA alleles and a predominance of GG alleles observed in patients with chronic periodontitis." (PMID 40142623, 2025). "Furthermore, for the LTF gene, the p.Lys47Arg SNP was more frequent in people with periodontitis compared to the controls, indicating an increased risk of developing the disease." (PMID 37372382, 2023). "LTF (lactotransferrin) has been found to have an effect on host immunological responses and has a potential antagonistic pleiotropy, suggesting that it may be protective against caries in addition to being predisposed to localized aggressive periodontitis." (PMID 36360315, 2022). "Albumin and Thioredoxin were up-regulated in periodontitis cases, while Cystatins (mainly S, SA, SN) and Lactotransferrin were down-regulated." (PMID 36355174, 2022). "A number of these genes were also significantly increased in aging and periodontitis tissues (e.g., ANXA1, HMGB1, S100A8, S100A9, APOE/ß2-GPI, LTF, TSLP)." (PMID 38098978, 2023). "In this study, both PIP and Lactotransferrin were down-regulated in pregnant women with periodontitis (OP and NP) when compared to OWP and NWP (Lactotransferrin was down-regulated 5-fold and 3-fold in OP and NP, respectively)." (PMID 36355174, 2022).
endometritis (6 papers, 2012 to 2024). An acute or chronic, usually bacterial infectious process affecting the endometrium. "Specific mRNA expression patterns of C3, C2, LTF, PF4, and TRAPPC13 are present in the blood and endometrium of dairy calves with subclinical endometritis." (PMID 37756095, 2023). "The levels of the PRLR, LTF, CLA-DRB3.2, beta defensin, TLR2, TLR4, and CCL5 genes were significantly up-regulated in postparturient goats with endometritis compared to tolerant ones, while the GPX4, GST, SOD3, CAT, and ATOX1 gene patterns demonstrated the opposite tendency." (PMID 39195794, 2024). "Additionally, C3, C2, LTF, PF4, and TRAPPC13 had unique mRNA expression patterns in the blood and endometrial tissue of dairy cows with subclinical endometritis." (PMID 37368756, 2023). "Additionally, in contrast to cows with sub-clinical endometritis, the gene expression profiles of C3, CXCL8, LTF, TLR2, and TRAPPC13 were temporally changed in healthy cows’ circulating WBC during the postpartum period." (PMID 37756095, 2023).
glioblastoma (6 papers, 2016 to 2025). The most malignant astrocytic tumor (WHO grade IV). "While LTF has been reported as a tumor suppressor and immune modulator in PCa42, a recent study in glioblastoma multiforme demonstrated that high LTF expression was associated with worse survival and increased immune cell infiltration." (PMID 41258098, 2025). "In glioblastoma, OPALIN, LTF, IL2RA, and SLC17A7 were implicated in Temozolomide resistance through pathways related to epithelial differentiation and angiogenesis." (PMID 41020875, 2025). "LTF suppressed and even reversed epithelial-to-mesenchymal transition process in oral squamous cell carcinoma and glioblastoma." (PMID 35096061, 2022). "In glioblastoma treated with Temozolomide, the models prioritized OPALIN, LTF, IL2RA, and SLC17A7 as candidate resistance related genes." (PMID 41020875, 2025). "For instance, interactions between LTF and ADAMTS16 in glioblastoma indicate a possible role in epithelial to mesenchymal transition." (PMID 41020875, 2025).
influenza (6 papers, 2013 to 2024). An acute viral infection of the respiratory tract, occurring in isolated cases, in epidemics, or in pandemics; it is caused by serologically different strains of viruses (influenzaviruses) designated A, B, and C, has a 3-day incubation period, and usually lasts for 3 to 10 days. "Furthermore, LTF and LCN2 also belong to the core genes associated with clinical severity in influenza infections, while LTF and S100A9 were associated with a higher mortality in patients with COVID-19 disease." (PMID 39409176, 2024). "In comparison, three patients had high activation of only a subset of influenza-connected genes PRTN3, LTF, PGLYRP1, DEFA1B, DEFA1, DEFA4, ELANE, and MPO." (PMID 34335605, 2021). "Incubation of influenza-infected BALF with neutrophils did not significantly alter the gene expression of cathelicidin, S100A8, S100A9, lactotransferrin, pentraxin-3, and MMP9 (data not shown)." (PMID 23467809, 2013).
osteosarcoma (6 papers, 2013 to 2025). A usually aggressive malignant bone-forming mesenchymal neoplasm, predominantly affecting adolescents and young adults. "The overexpression of LTF promotes the proliferation, migration, and invasion of osteosarcoma cells." (PMID 39351154, 2024). "Subsequently, we identified 4 key genes correlated with the survival of osteosarcoma patients, including lactoferrin/lactotransferrin (LTF), C10orf107, histone cluster 1 H2ak (HIST1H2AK), and nexilin F-actin binding protein (NEXN)." (PMID 35096061, 2022). "Four key genes (C10orf107, HIST1H2AK, NEXN, and LTF) were found to be correlated with the prognosis of osteosarcoma patients." (PMID 35096061, 2022). "The results showed that the overexpression of LTF inhibited the proliferation of osteosarcoma cells." (PMID 35096061, 2022). "The key gene we identified, such as LTF, could be a prognosis biomarker and therapeutic drug target for osteosarcoma." (PMID 35096061, 2022). "In conclusion, LTF may serve as a prognostic biomarker for osteosarcoma." (PMID 35096061, 2022). "Moreover, the upregulation of LTF also promoted the migration and invasion of osteosarcoma cells." (PMID 35096061, 2022). "The expression of C10orf107 and NEXN was positively correlated with poor survival of osteosarcoma patients, whereas the expression of HIST1H2AK and LTF was negatively correlated with poor survival of osteosarcoma patients." (PMID 35096061, 2022). "Four key genes (LTF, C10orf107, HIST1H2AK, and NEXN) were identified to be correlated with the prognosis of osteosarcoma patients." (PMID 35096061, 2022). "The results showed that the expression of LTF was lower in osteosarcoma samples compared with that in normal controls." (PMID 35096061, 2022).
asthma (5 papers, 2019 to 2022). "Most DEGs of this term, including DEFA3, DEFA4, ELANE, and LTF, encode antimicrobial peptides in neutrophils, indicating that the upregulated antimicrobial immune response in the AR-asthma group is mainly mediated by neutrophils." (PMID 36569909, 2022). "LTF which is an iron-binding glycoprotein has been shown upregulated during asthma development in our study as also reported by other studies." (PMID 32770056, 2020). "The results of the qPCR showed that during the weed pollen season, the expression levels of ELANE and LTF in the AR-asthma group were significantly higher than those in the AR group, whereas the expression levels of PF4 in the two groups were not significantly different." (PMID 36569909, 2022). "Outside the weed pollen season, the expression levels of LTF, PF4, and ELANE in the AR-asthma group were significantly higher than those in the AR group." (PMID 36569909, 2022). "A recent study found 5 hub genes (SERPINB2, SERPINB4, LTF, MUC5B, and CST4) related to the pathogenesis of asthma in bronchial and nasal cells." (PMID 36076228, 2022).
gastric cancer (5 papers, 2011 to 2024). A primary or metastatic malignant neoplasm involving the stomach. "We performed cDNA microarray analysis to identify the downstream target genes of SOX2 in gastric cancer cells, and found that many tumor-associated genes exhibited significant changes in expression after SOX2-overexpression (e.g., LTF, PPP2R1B, TGFBR2, SERPINE1, MMP9, HMGA1 and SOX9)." (PMID 21304604, 2011).
metabolic syndrome (5 papers, 2013 to 2022). A cluster of metabolic risk factors for CARDIOVASCULAR DISEASES and TYPE 2 DIABETES MELLITUS. "Overall, the presence of the CT variant compared to the TT variant of LTF rs2239692 significantly decreased the odds of developing metabolic syndrome in obese subjects (OR = 0.53, 95% CI = 0.31–0.91, p = 0.0204)." (PMID 32957486, 2020). "We found significant differences in the genotype frequencies of LTF rs2239692 between MHO and MUHO subjects, with the CT variant associated with lower odds of developing metabolic syndrome than the TT variant." (PMID 32957486, 2020). "In the present study, an inflammatory marker that was increased in expression in the metabolic syndrome individuals was lactotransferrin, which has been shown to be increased in concentration during most inflammatory reactions." (PMID 24358323, 2013).
pancreatic cancer (5 papers, 2014 to 2023). "The E3 ligase NEDD4 like E3 ubiquitin protein ligase (NEDD4L), a novel ferroptosis suppressor in human pancreatic cancer cells, has been found with a role in regulating iron metabolism by targeting iron-binding transport protein lactotransferrin (LTF)." (PMID 34485285, 2021). "NEDD4L mediates the degradation of the iron-binding transport protein lactotransferrin (LTF) by ubiquitination to hinder the malignant biological behavior of pancreatic cancer." (PMID 34869021, 2021). "LTF plays important role in innate immunity, and it has been shown that LTF is significantly down-regulated in pancreatic cancer." (PMID 24708694, 2014). "Examples of consistent protein expression changes all the way up to clinical diagnosis of pancreatic cancer, were; gelsolin (GSN), apolipoprotein A4 (APOA4), coagulation factor 12 (F12) and lactotransferrin (LTF)." (PMID 24708694, 2014).
Autoimmunity (4 papers, 2015 to 2025). The occurrence of an immune reaction against the organism's own cells or tissues. "Interestingly, when |Δβ| ≥ 0.1 (simultaneously p < 0.01), 4 of the 28 DMGs—HLA-DPB2, HLA-DRB1, PPP2R5C, and LTF, which all mapped from more than one CpG site—are all associated with autoimmunity." (PMID 34539625, 2021). "Similar findings were reported in a human tears study, which demonstrated increase in cystatin S and lactotransferrin levels in tears collected from patients with autoimmune conditions." (PMID 26779447, 2015).
dry eye (4 papers, 2020 to 2023). "Interestingly, this downregulation of proteins with antibacterial activity like lysozyme and lactotransferrin may be related to the increased risk of infectious diseases of the ocular surface in dry eye patients." (PMID 33372592, 2020). "Lipocalin-1, a major component of normal tears, along with lysozyme C and lactotransferrin, both antimicrobial proteins, are produced by the lacrimal gland and are also downregulated in tears from dry eye patients." (PMID 33372592, 2020). "For instance, LCN1, PIP, LTF, and SG2A1 were substantially reduced in dry eye, while AZGP1, LEG7, CST4, CST1, and ACTB were diminished in MGD." (PMID 35685417, 2022). "Based on our study, attention should be paid to genes such as LCN1, LTF and SCGB2A1, which had lower expression levels in pterygium, to determine whether they are directly involved in the development of pterygium and dry eye." (PMID 32411530, 2020).
endometriosis (4 papers, 2022 to 2025). The growth of functional endometrial tissue in anatomic sites outside the uterine body. "Among them, the downregulated expression of lactotransferrin in the endometrium was confirmed for endometriosis, independently of the phase of the menstrual cycle." (PMID 35204508, 2022). "Lactotransferrin is used as a marker of neutrophil granulocyte activation and was shown to be present at lower concentrations in the peritoneal fluid of women with minimal endometriosis (stage I of rASRM classification)." (PMID 35204508, 2022).
melanoma (4 papers, 2020 to 2023). A malignant, usually aggressive tumor composed of atypical, neoplastic melanocytes. "A recent study found that LTF deficiency enhanced lung metastasis of melanoma in an LTF KO mouse model, which was related to the enhancing of the TLR9 pathway." (PMID 35096061, 2022). "Accordingly, in a recent study, LTF deficiency in mice was shown to promote the metastatization of melanoma cells to lungs, as compared to LTF +/+ mice." (PMID 35053267, 2022). "Because the 4 genes IGHV1-18, CXCL11, LTF and HLA-DQB1 are associated with tumor immunity, we used the TIMER database to analyze the correlation between the prognosis of these 4 genes and the infiltration of immune cell subtypes in melanoma." (PMID 33585219, 2020). "Compared with the normal melanocytes, IGHV1-18, CXCL11 and HLA-DQB1 were highly expressed in melanoma cell line A375, A815 and SK-MEL-28, and LTF was downregulated in melanoma cell line A375, A815 and SK-MEL-28, and both had statistical significance (P < 0.05)." (PMID 33585219, 2020). "LTF may play a protective role in melanoma metastasis by inducing differentiation and apoptosis of myeloid-derived suppressor cells (MDSCs) and up-regulating TLR9 expression." (PMID 33585219, 2020). "In this study, we focused on the immune infiltrating status in melanoma and selected IGHV1-18, CXCL11, LTF and HLA-DQB1 from immune cell infiltration cluster as immune cell infiltration-related DEGs through the analysis of differences in melanoma samples and the construction of prognostic models." (PMID 33585219, 2020).
lung carcinoma (3 papers, 2012 to 2024). "This suggested that UCH-L1 and LTF could be novel diagnostic and therapeutic targets for lung cancer metastasis diagnostic markers." (PMID 23122428, 2012). "By intersecting these top DEGs, we recognized seven genes potentially involved in the pathogenesis of both SSc and lung cancer: SCN7A, AGTR1, WIF1, PRKG2, LTF, AQP4, and COL10A1." (PMID 39744538, 2024). "This was reversed during the lung cancer condition where UCHL1 up-regulated and the LTF highly down-regulated." (PMID 23122428, 2012). "The cluster 4 had two-lung cancer related genes ubiquitin thiolesterase (UCHL1) and Lactotransferrin (LTF)." (PMID 23122428, 2012).